CCR7 (C-C motif chemokine receptor 7)
Diseases named in the same sentence as CCR7 in open-access papers (continued):
Sharing a sentence is not in itself a finding about the gene and the disease.
atherosclerosis (31 papers, 2010 to 2025). A disease characterized by the build-up of fatty material and calcium deposition in the arterial wall resulting in partial or complete occlusion of the arterial lumen. "Other studies suggest that mice with macrophage-specific low-density lipoprotein-receptor-related protein 1 (LRP1) deficiency or statin treatment showed increased CCR7 expression in lesional macrophages to promote the atherosclerosis regression." (PMID 36012557, 2022). "Of note, the role of CCR7 during atherosclerosis remains debated with studies reporting that CCR7-deficient mice display smaller, similar and increased plaque area." (PMID 39649554, 2020). "CCR7 and its ligands have previously been related to various inflammatory disorders including atherosclerosis and have also been linked to development of HF." (PMID 25398010, 2014). "Naive T cells, expressing Cd28+Ccr7+, increase IL-7 signaling and support T cell survival, differentiation as well as proliferation in more advanced atherosclerosis." (PMID 39399488, 2024). "The expression of CCR7 in macrophage is essential for decreasing the macrophage amount in plaques and promoting the regression of atherosclerosis, by interacting with its specific ligands CCL19 and CCL21." (PMID 34345249, 2021). "In order to investigate the role of CCR7/CCL19/CCL21 in atherosclerosis progression, the plaque-containing arterial segments from apo E-deficient mice were transplanted into the wild-type recipient normolipidemic mice to induce an atherosclerosis regression." (PMID 34345249, 2021). "Another target for promoting the regression of atherosclerosis is through the activation of the chemokine receptor CCR7-dependent emigration pathway in macrophages." (PMID 31357630, 2019). "In line with this, the CCR7/CCL19/CCL21 dyad has also been implicated in various disorders characterized by inflammation and matrix remodeling such as atherosclerosis, rheumatoid arthritis and inflammatory bowel disease." (PMID 25398010, 2014). "We then determined that LXR is required for maximal effects on plaque CD68+ cell expression of CCR7 as well as monocyte-derived cell egress during atherosclerosis regression in mice." (PMID 22934038, 2012). "CCR7 and its ligands have previously been related to various inflammatory disorders such as rheumatoid arthritis, inflammatory bowel disease, and atherosclerosis." (PMID 22427939, 2012). "HDAC7 appears to be upregulated in mouse models of atherosclerosis, consistent with the very low expression of CCR7 in CD68+ cells from atherosclerotic plaques." (PMID 22163030, 2011). "We previously reported in a transplant-based mouse model of atherosclerosis regression that the rapid depletion of plaque CD68+ cells was through a migration process dependent upon the induction of chemokine receptor CCR7." (PMID 22163030, 2011). "However, upregulation of CCR7 will unexpectedly accelerate atherosclerosis regression in a bone marrow transplantation experiment." (PMID 34345249, 2021). "Indeed, the activation of CCR7-dependent immigration of monocytes from the lesion site was previously suggested to be one of the mechanisms by which statin treatment can decrease atherosclerosis." (PMID 33936102, 2021). "During regression of atherosclerosis, foam cells may acquire characteristics of DC, shown by upregulated expression CCR7 allowing them to migrate to lymph nodes." (PMID 34975863, 2021). "A recent study indicated that statins could activate the CCR7 emigration pathway in macrophages to accelerate the regression of atherosclerosis." (PMID 26309120, 2015). "Furthermore, the CCL21 molecule and its receptor CCR7 have a possible role in the development of atherosclerosis by recruiting T cells and macrophages to the atherosclerotic lesions and by promoting inflammatory responses in these cells." (PMID 20461788, 2010).
atherosclerosis (continued). "Cluster 5 showed a gene expression profile that was characterized by the expression of Btla, Ccr7, Tbc1d4, Ccl22, and Ly6d revealing a population of MoDC/DC cells present in the aortas that were independent of the atherosclerosis predisposition or the diet." (PMID 35159221, 2022). "Therefore, it is logical to assume that cTfh cells might contribute to pathogenesis of atherosclerosis through the enrichment of PD-1+CCR7− efficient subset and inflammatory cytokines secretion." (PMID 33465845, 2021). "However, the role of CCR7 in atherosclerosis is more complex." (PMID 31357630, 2019). "In intimal medullary cells, reverse transendothelial migration dependent on CCR7 and CCL19 protect normal arterial intima during atherosclerosis." (PMID 33424012, 2020). "The data demonstrate that the regression of atherosclerosis is possible with factors such as HDL, LXR, and CCR7 playing key roles." (PMID 22934038, 2012). "In atherosclerosis, the absence of CCR7 not only impedes the infiltration of inflammatory cells into the vascular wall but also retards the progression of atherosclerotic plaques." (PMID 38785203, 2024). "While many immune pathways were enriched in the upregulated DEGs (e.g., CXCR5, IL21R, CCR7 and CD22) (A,C), pathways such as “lipid and atherosclerosis’ and “fluid shear stress and atherosclerosis” were enriched in the downregulated DEGs (such as NOS3, KLF2 and KLF4)." (PMID 37218991, 2023). "TEM and TEMRA cells remain CCR7- and maintain both memory and flexibility of cytokine gene expression, but they also upregulate CX3CR1 which allows them to bind to vascular endothelium and promote atherosclerosis." (PMID 32249825, 2020). "In contrast, we found that expression of chemokine (C-C motif) receptor 7 (Ccr7) and liver X receptor alpha (Lxr) was downregulated in response to atherosclerosis regression, not upregulated (not shown)." (PMID 24586211, 2014). "As TEM are antigen-experienced and long-surviving cells that have lost CCR7 and express HLA-DR, CXCR3, and CCR5, this finding strengthens the concept that the understanding of the inflammatory pathogenesis of atherosclerosis requires careful cellular subphenotyping." (PMID 23130116, 2012). "However, as CCR7 is expressed on several lymphocytes, including cells that express adhesion molecules required for homing to nonlymphoid tissues, the deficiency of CCR7 could also impair the trafficking of cells other than CD4 lymphocytes during atherosclerosis." (PMID 23130116, 2012). "Recent studies have found that deletion of CCR7 not only leads to reduced plaque content in mice, but also results in disturbed access of T cells to and from the site of plaque inflammation.The ApoE-/- mice lacking CD4+ T cells show reduced atherosclerosis." (PMID 39399488, 2024). "Our findings show that enhancing atherosclerosis regression after PCL will require targeting regulatory genes at the top of the regulatory hierarchy (e.g., master regulators) rather than individual effector genes (e.g., Ccr7 and Lxr) or specific pathways, such as TEML or cell proliferation." (PMID 24586211, 2014).
autoimmune disease (30 papers, 2007 to 2026). A disorder resulting from loss of function or tissue destruction of an organ or multiple organs, arising from humoral or cellular immune responses of the individual to their own tissue constituents. "Low expression of CCR7 (CCR7low) is associated with activated T follicular helper cells (Tfh) and linked to ongoing autoreactive antibody production in several autoimmune diseases." (PMID 41244589, 2025). "Misregulation of C-C chemokine receptor 7 (CCR7) has been linked to multiple autoimmune diseases including systemic lupus erythematosus, multiple sclerosis, and ankylosing spondylitis." (PMID 41097007, 2025). "Chemokine receptor CCR7 in DCs is associated with the pathogenesis of chronic inflammation, autoimmune diseases, and cancer." (PMID 36601262, 2022). "It reported that CCL19 and the paired CCR7 were are associated with autoimmune diseases like rheumatoid arthritis and enteropathy." (PMID 34046056, 2021). "Since Ccr7 deficiency in mice results in morphological and functional alterations, which are also characteristic for various human autoimmune diseases, we sequenced part of the CCR7 locus in 160 autoimmune patients and 40 healthy controls." (PMID 17587445, 2007). "Among the circulating memory Tfh cells, CCR7+ memory Tfh cells can migrate into B cell follicles and promote humoral responses, and activated CCR7-PD-1+ memory Tfh cells in the secondary lymphoid tissues also enhance the humoral responses, associated with the development of autoimmune diseases." (PMID 35126400, 2022). "Among circulating memory Tfh cells, CCR7+ memory Tfh cells can migrate into B cell follicles and promote humoral responses, and activated CCR7-PD-1+ memory Tfh cells in secondary lymphoid tissues also enhance humoral responses, associated with the development of autoimmune diseases." (PMID 26231034, 2015). "Nevertheless, mutations in such regulatory regions of the gene could lead to decreased CCR7-expression and therefore increases the susceptibility of individual subjects to develop autoimmune disease." (PMID 17587445, 2007). "Based on data derived from Ccr7-deficient mice we tested the hypothesis that mutations in the CCR7 gene might be associated with the development of autoimmune diseases in humans." (PMID 17587445, 2007). "This leaves the possibility open that rare mutations occurring in regulatory regions of the CCR7 gene could result in increased susceptibility to the development of autoimmune diseases in individual subjects." (PMID 17587445, 2007). "By binding and activating the chemokine receptors, CC chemokine receptor (CCR) 6 and CCR7, they can induce the mobilization of intracellular calcium ions, which mediates the effects of cancer, various autoimmune diseases, and antimicrobial responses." (PMID 40003312, 2025). "Drugs used to treat autoimmune diseases typically produce systemic immune suppression, and ShK domain peptides can target the Kv1.3 channel to selectively inhibit CCR7-TEM lymphocytes and reduce this side effect." (PMID 39452877, 2024). "Blocking the CCL19/CCR7 axis is a potential therapeutic option for the treatment of autoimmune diseases." (PMID 35702353, 2022). "Collectively, these results suggest that the CCL19/CCR7 axis plays an important role in the progression of autoimmune diseases and is closely related to immune regulation at the site of the lesion." (PMID 35702353, 2022). "T cells derived from autoimmune disease patients stimulated with autoantigen have a similar mixed CCR7/CD45RO expression profile as pathogen-stimulated T cells, yet autoreactive T cells are amenable to Kv1.3 inhibitors." (PMID 28248292, 2017). "Also, CCR7+/RELB+/IRF1+ T cells had been revealed as an independent responsor in JIA among other types of autoimmune diseases, severing as potential therapeutic target." (PMID 40406113, 2025). "Recent studies have highlighted the diverse roles of CCR7 across autoimmune diseases." (PMID 41244589, 2025).
autoimmune disease (continued). "The role of CCR7 is not sufficiently understood, but CCR7 stimulation causes dendritic cell maturation; moreover, CCR7 knockout mice more frequently develop autoimmune disorders." (PMID 38612597, 2024). "Furthermore, the results largely exclude the possibility that rare sequence variants within the coding sequences, flanking intron sites and the CCR7 core promoter accumulate in subjects suffering from autoimmune diseases investigated in this study." (PMID 17587445, 2007). "Notably, the regulatory axis centered around hsa-miR-622–CXCR4/CCR7 suggests that immune cell migration may represent a shared pathological basis for these two autoimmune diseases." (PMID 41481752, 2026). "Moreover, misguidance of immune cells due to impaired CCR7 signaling may lead to autoimmune diseases." (PMID 31137829, 2019). "Across the T cell populations of these autoimmune diseases, CCR7, RELB, and IRF1 were notably highly expressed in JIA T cells, which revealed that CCR7+/RELB+/IRF1+ T cells independently response for JIA." (PMID 40406113, 2025). "Previously, the expression of Kv1.3 potassium channels, the target of T cell-mediated autoimmune diseases, was decreased by scorpion toxin ADWX-1 blocker in CD4+CCR7- T cells overexpressing Kv1.3 channels." (PMID 24386436, 2013). "We have provided mechanistic evidence that CCR7 expression is kinetically upregulated in the absence of Sema3E suggestive of a novel target to modulate unwanted DC migration, e.g. in allergic or autoimmune diseases." (PMID 34185781, 2021). "Similar to the CCL19/CCL21/CCR7 axis, the CCL20/CCR6 axis serves an essential role in the recruitment of inflammatory cells in the immune response and may contribute to a variety of autoimmune diseases, such as MS, IBD, psoriasis, and RA." (PMID 35702353, 2022). "However, they observed increased proportions of PD1+CCR7+ TFH in CVID with autoimmune diseases as compared with CVID without autoimmune diseases and controls." (PMID 32618135, 2020). "In this regard, it has been published that the chronic absence of CCR7 may lead to the development of autoimmune diseases given the role of CCR7 in the maintenance of the tolerance." (PMID 24305507, 2013).
Autoimmunity (28 papers, 2007 to 2025). The occurrence of an immune reaction against the organism's own cells or tissues. "Animal studies have shown that CCR7-deficient mice are prone to developing systemic multiorgan autoimmunity." (PMID 40726550, 2025). "CCR7-deficient mice were prone to generalized multi-organ autoimmunity, which shared similarities with SLE-associated multi-organ involvement." (PMID 34220794, 2021). "Studies found that CCR7 deficiency leads to the development of multi-organ autoimmunity, chronic renal disease and autoimmune diabetes." (PMID 33853536, 2021). "The second study provides evidence that homeostatic proliferation of pro-inflammatory CD4+ and CD8+CCR7-RA- or CD45RA+ memory T cells with a restricted T cell repertoire drives the risk for secondary autoimmunity." (PMID 32539719, 2020). "These events are central for maintaining peripheral tolerance, as Treg cells require LN occupancy and CCR7 signaling for their activation and function, and the loss of CCR7 signaling is associated with spontaneous autoimmunity." (PMID 31428105, 2019). "We recently demonstrated that Ccr7-deficient mice are prone to develop generalized multi-organ autoimmunity and spontaneously display symptoms of human connective tissue autoimmune diseases." (PMID 17587445, 2007). "Due to these defects, Ccr7-deficient mice spontaneously develop multi-organ autoimmunity showing symptoms similar to those observed in humans suffering from connective tissue autoimmune diseases." (PMID 17587445, 2007). "Since CCR7 and its ligands have been linked to autoimmunity, these studies may provide insight into mechanisms that can be targeted to control autoimmune responses." (PMID 41097007, 2025). "Although no variant of the Ccr7 gene is found to be directly linked to diseases in humans, it is claimed that the Ccr7 variant could potentially lead to increased susceptibility to autoimmunity." (PMID 35281921, 2022). "It was also noticed that CCR7-deficient mice develop lymphoid at sites such as the stomach, lung, and colon; however, it is not exactly known about the extent of ectopic lymphoid structure contribution to autoimmunity establishment and maintenance." (PMID 35874608, 2022). "Nevertheless, the decreased luciferase activity observed in cells transfected with the promoter region bearing the -60 C/T mutation suggests that this CCR7 variant could potentially lead to increased susceptibility to autoimmunity." (PMID 17587445, 2007). "Furthermore, the lupus-associated polymorphism in human FCGR2B (rs1050501) that results in receptor dysfunction is associated with increased CCR7 expression on DCs following IgG IC stimulation, driving enhanced migration to the T cell zone of lymph nodes, propagating autoimmunity and inflammation." (PMID 35619690, 2022). "To evaluate this possibility, we assessed the presence of spontaneous autoimmunity/autoinflammation in multiple organs of WT, Ccr4−/−, Ccr7−/−, and DKO mice." (PMID 37266571, 2023). "In the long-term, CCR7-defficient mice were prone to develop generalized multi-organ autoimmunity (mainly in mucosa) although had a normal life span and did not suffer from clinically aggressive diseases." (PMID 33841445, 2021). "SS-like autoimmune lesions in the CCR7 KO and RelB KO mice occur through the impairment of T cell differentiation or selection in the thymus." (PMID 28587293, 2017). "A subgroup of TFH with central memory/resting profile expressing chemokine receptor 7 (CCR7) predominates in normal individuals, while in patients with autoimmune conditions, TFH with high expression of programmed-death 1 (PD-1) and low CCR7 are more abundant." (PMID 27069935, 2016). "A subgroup of TFH defined by high PD-1 and low CCR7 expression has been demonstrated in patients with autoimmune conditions." (PMID 27069935, 2016). "We therefore investigated the cellular mechanism for suppressive function of Treg cells via CCR7 in autoimmunity using mouse models and human samples." (PMID 20052419, 2010).